TERT (telomerase reverse transcriptase)
Diseases named in the same sentence as TERT in open-access papers (continued):
Sharing a sentence is not in itself a finding about the gene and the disease.
tumor (continued). "Moreover, PIWI proteins were determined in one non-tumor cell line developed from human pancreatic duct transduced with a retroviral expression vector containing the human TERT gene (hTERT-HPNE)." (PMID 32357464, 2020). "Indeed numerous reports show that cancer stem cells (CSC) depend on TERT for their ability to self-renew and for tumor propagation." (PMID 32630460, 2020). "Of note, TERT mRNA expression levels were not different when considering other genetic alterations present in the tumours, such as BRAF, NRAS mutations and RET/PTC or PAX8/PPARγ rearrangements (Figure A1)." (PMID 32659948, 2020). "Moreover, NCOA3 is positively correlated with TERT expression in HCC tumor tissues, and high expression of both NCOA3 and TERT predicts a poor prognosis in HCC patients." (PMID 33239622, 2020). "Besides CCND1 and TERT, 30 additional genes were altered in at least two tumor samples in our cohort, either through SNV or SV." (PMID 33384420, 2020). "TERT alterations (TERTmod) were detected in 270 of the 2519 tumor samples (11%)." (PMID 32024817, 2020). "Relative telomere length ranged between 0.19 and 3.62 with median values of 1.02 in tumor-surrounding skin, 0.81 in tumors without TERT promoter mutations and 0.72 in tumors with the promoter mutations." (PMID 32409749, 2020). "Furthermore, we showed that there was a strong correlation of the expression of PUF60 and TERT in RCC tumor tissues and RCC cell lines, and the patients with high expression of PUF60 and TERT had significantly shorter survival." (PMID 33061812, 2020). "Unlike most conserved self-tumor antigens, TERT expression is additionally regulated by mutations in the promoter region." (PMID 32630460, 2020). "Overall, however, only 3% of all TERT expressing tumor samples present with TERT amplification." (PMID 31757062, 2019). "The results of DNA samples from 40 cancer and 25 normal lung tissues showed a good diagnostic potential of selected RCGY sites in regulatory regions of MYF6, SIX6, RXRG, LHX1, RASSF1A and TERT genes with relatively high sensitivity (80.0 %) and specificity (88.0 %) of LC detection in tumor DNA." (PMID 31526458, 2019). "Furthermore, TERT expression was reduced in the tumor tissues from FOXD2-AS1-silencing mice group compared with those from the scramble mice group." (PMID 31024447, 2019). "Strikingly, TERT mRNA was only expressed in the tumor with concomitant TERT promoter and BRAFV600E mutations, whereas neither differences in expression of ETS-factors nor the downstream target cyclin D1 were observed." (PMID 31391125, 2019). "However, other groups argue about the increased potential for tumor development in TERT-immortalized cells." (PMID 30627420, 2019). "It has been proposed that plasma circulating TERT levels could derive from activated lymphocytes and therefore they may be indicative of the induction of tumor immune responses." (PMID 31772219, 2019). "Based on these, we developed an ultra-sensitive, urine-based assay called Uromonitor®, capable of detecting trace amounts of TERT promoter (c.1-124C > T and c.1-146C > T) and FGFR3 (p.R248C and p.S249C) hotspot mutations, in tumor cells exfoliated to urine samples." (PMID 31921291, 2019). "Studies also show that TERT promoter mutations correlate with poorer outcomes and an increase in aggressiveness of the tumor, even if they do not coincide with BRAF mutation." (PMID 30089490, 2018).
tumor (continued). "The acquisition of additional genetic changes, such as TERT promoter mutations and CDKN2A homozygous deletions, may play a role in tumor progression." (PMID 29739933, 2018). "In EBV-positive tumor cells, the lytic cell cycle induced by TERT inhibition may be exploited to sensitize cells to antiviral drugs such as GCV." (PMID 29643934, 2018). "Although TERC has broad tissue distribution and is constitutively present in normal and tumor cells, the expression of TERT is usually repressed in normal somatic cells and is essential for unlimited cell growth, thus playing a critical role in tumor formation and progression." (PMID 29643934, 2018). "Indeed, in most TERT-positive tumour cells, most of the TERTp region contains hypermethylated CpG islands." (PMID 29751586, 2018). "Due to poor quality of the RNA extracted from older paraffin embedded tumor samples in our patient cohort, analysis of TERT expression and/or telomerase activity is extremely limited to further support our hypothesis." (PMID 29463038, 2018). "Notably, even replicative tumor cell lines were shown to lack relevant nuclear TERT protein, but to induce telomerase activity in the nuclear compartment by cytoplasmic-to-nuclear transfer of TERT protein only upon stimulation." (PMID 30472697, 2018). "Despite the already stated role of TERTp mutations in hepatocarcinogenesis as an early event in tumour progression and the cause of higher TERT expression, TERT amplification does not show a clear correlation with progression." (PMID 29751586, 2018). "Interestingly, as previously discussed about tumor suppressive effects exerted by different miRNAs, oncogenic miRNAs stimulated the expression of TERT by promoting the expression and function of JAK-STAT pathway." (PMID 29614790, 2018). "However, in most cancers enhanced TERT transcription, due to various mechanisms, and consequent telomerase rejuvenation, imparts tumor cells an infinite capability to surmount proliferative barrier through telomere stabilization." (PMID 30026606, 2018). "It is noted that some well-established associations like mutations in ATRX and DAXX (death-domain associated protein) for ALT as well as TERT promoter mutations for telomerase-positive cells are absent in many tumor samples." (PMID 29776332, 2018). "Specific non-coding RNA interaction with TERT has been reported in multiple types of tumours." (PMID 29751586, 2018). "In the upcoming section we summarize how tumor suppressor miRNAs negatively regulate TERT." (PMID 29614790, 2018). "In EBV-driven malignancies, besides sustaining the latency program required for the EBV-driven transformation, TERT may promote EBV tumor progression by enhancing the kinetics of cell proliferation." (PMID 29643934, 2018). "Interestingly, leptin has also been shown to upregulate the TERT and thereby lead to immortalization of tumor cells in HCC." (PMID 30228976, 2018). "Importantly, TERT inhibition also sensitizes EBV-positive tumor cells to antiviral therapy and enhances the pro-apoptotic effects of chemotherapeutic agents." (PMID 29643934, 2018). "It seems clear that tumor suppressor miRNAs are strategically inhibited to enhance TERT expression." (PMID 29614790, 2018). "In addition to data on 1p/19q co-deletion, TERT promoter and IDH mutation, for 1955 of the tumours we had information on EGFR amplification and CDKN2A deletion status." (PMID 29460007, 2018). "The shuttle of TERT between nucleus and cytoplasm in tumor cells could be regulated by certain mechanisms such as phosphorylation, depending on cell cycle or cellular immortalized transformation." (PMID 28460432, 2017). "While previous groups have reported TERT promoter mutations in atypical samples, we find that these events were limited to recurrent samples only, and not present in de novo tumours." (PMID 28195122, 2017). "TERT RNA-transfected human DCs can effectively stimulate CTLs and induce tumor cell lysis." (PMID 28477011, 2017).
tumor (continued). "To establish whether TERT promotes cisplatin resistance in vivo, we subcutaneously inoculated tumor xenografts derived from 143B cells into NOD/SCID mice." (PMID 28765565, 2017). "However, technical difficulties in measuring TERT mRNA levels in tumor tissue limit its use as a prognostic marker." (PMID 28378855, 2017). "No patient was positive for a TERT promoter mutation in plasma and negative in its corresponding tumor tissue (100% specificity)." (PMID 29108273, 2017). "The tumor samples were screened for TERTp and ATRX/DAXX mutations, and TERT rearrangements." (PMID 29312603, 2017). "In addition, both n-3 and n-6 PUFA significantly inhibited telomerase activities due to the reduction of c-Myc-mediated TERT expression, which indicates the tumor-inhibitive potential of long-chain PUFA." (PMID 28038469, 2017). "Indeed, TERT is shared and actively expressed in about 85% of human tumours with various histological type." (PMID 29152058, 2017). "However, an increase in the number of CNA events was observed from low‐grade to high‐grade tumours, especially for concomitant gains of TERT, SDHA and RICTOR located on the p‐arm of chromosome 5." (PMID 27873319, 2017). "It is notable that all patients with TERT promoter mutations in plasma had corresponding mutations in matched tumor tissue and as such no false positive plasma samples were detected." (PMID 29108273, 2017). "Since the present study and previous studies demonstrated an association of TERT promoter mutations with larger tumor size of PTC, the large number of small tumors included in our study presumably resulted in an overall low prevalence of TERT promoter mutations." (PMID 26943032, 2016). "However, 76NE6 or 76NE6/TERT cells that stably expressed PAF developed the tumours in immunocompromised mice." (PMID 26843124, 2016). "According to our analysis, tumor size was larger in patients with TERT promoter mutations than in those without TERT promoter mutations." (PMID 27833153, 2016). "In conclusion, we present evidence that TERT promoter and CTNNB1 mutations have a high frequency in HCC of viral origin, particularly in HCV-related HCC, and are very specific to the tumor tissues given their constant absence in the autologous non-tumor cirrhotic tissues." (PMID 27276713, 2016). "We also examined expression levels of galectin-3 and TERT in tumor tissues from xenografted mice." (PMID 27494887, 2016). "Additionally, 3PO treatment at CT7 was more effective than at CT19 in terms of decreasing the expression of TERT, which also appeared to contribute to the observed decrease in the size of implanted neoplasms." (PMID 27079271, 2016). "They found that Ad-TERTp-E1A-EphA3 shRNA had 3.5- and 1,400- fold greater ability to kill EphA3 and TERT expressing tumor cells compared to Ad-TERTp-E1A-NC and Ad-ΔE1A-EphA3 shRNA, respectively, while had little effect on cells that modestly expressed EphA3 and TERT." (PMID 26980708, 2016). "However, the intensity of TERT staining was higher in HCC tissues compared to non-tumor liver samples (p = 0.001)." (PMID 27056898, 2016). "We further assessed tumor formation of TERT-SHED P20 in nude mice." (PMID 27044500, 2016). "No mutations were identified in any matched peri-tumor cirrhotic tissue confirming the somatic nature of TERT promoter mutations and their very-likely driver function in neoplastic transformation." (PMID 27276713, 2016). "Furthermore, the stem cell-related genes Oct4, Sox2 and TERT were upregulated in cisplatin-resistant cells, and cisplatin resistant cells were able to generate more tumor spheres than vehicle cells during primary and secondary sphere assay." (PMID 27102300, 2016). "A fixed-effects model was adopted, as heterogeneity was not significant between tumor size and TERT promoter mutations (P = 0.90, I2 = 0%)." (PMID 27833153, 2016). "Immunization against TERT may overcome tumour cell immune evasion by boosting the level of cytotoxic T cells specifically targeting the neoplasm." (PMID 26085010, 2015).
tumor (continued). "As hypothesized, increased TERT protein expression was observed in NPC tumor tissue and metastatic lymph nodes." (PMID 25435972, 2015). "Specifically targeting the TERT promoter mutations is an attractive approach, as TERT promoter mutations are exclusive to the tumor cells and are not present in surrounding normal tissue." (PMID 26194807, 2015). "In normal cells, only phosphorylated TERT regulates telomerase activity following nuclear translocation, however, tumor cells that constitutively exhibit high levels of telomerase activity express the TERT protein in the phosphorylated form, which is located in the nucleus." (PMID 25435972, 2015). "Furthermore, we show that monoallelic TERT expression is highly prevalent in certain tumor types and widespread across a broad spectrum of cancers." (PMID 26657580, 2015). "Similarly, immunization of mice with a 1:1 mixture of dendritic cells (DCs) transfected with VEGFR-2 and TERT mRNAs in vitro was shown to have a synergistic anti-tumour effect." (PMID 26085010, 2015). "However, 90% of human cancers have very high TERT activity, which enables them to divide continuously to drive tumor growth." (PMID 26194807, 2015). "Ultimately, the resulting TERT expression led to aberrant telomerase enzymatic activity in terminally differentiated cells and abnormally long telomeres, thereby bypassing the telomere shortening tumor suppressor pathway." (PMID 26194807, 2015). "Thus, Ad- TERTp-E1A-1504 does not harm normal cells but has dual inhibiting and killing effects on TERT- and EphA3-positive tumor cells, and this effect is mediated by the AKT/mTOR signaling pathway via induction of autophagy." (PMID 25978371, 2015). "The adverse effect of only TERT promoter mutations was statistically significant in a model that did not include tumor grade and age (HR = 2.18; 95% HR CI 1.31 – 3.63; P = 0.003)." (PMID 25797251, 2015). "These tumor cell lines have sufficient telomerase activity to maintain an immortal phenotype, but so do tumor cells without these TERT promoter mutations." (PMID 26194807, 2015). "Moreover, overexpression of human TERT (hTERT) is reported to be correlated with advanced invasive stage of the tumor progression and poor prognosis." (PMID 26497550, 2015). "The activity of the TERT promoter has been shown to be higher in cancer cell lines than in transformed cells lines similar to those used in the present study therefore, the possible effects of GSE4 on TERT expression in tumour cells should be tested in future studies." (PMID 26571381, 2015). "Since the TERT protein is proposed to co-activate NFκB to enhance gene-expression of e.g IL-6, TNFα and other pro-inflammatory cytokines, contributing to tumor progression, we analyzed the relative mRNA levels on thirty-six AML patients with different rs2853669 genotypes." (PMID 26298771, 2015). "Indeed, we found that combined vaccine treatment induced cytotoxicity more robustly in tumour cells expressing either VEGFR-2 or TERT (MS1 and EL4 cells, respectively) and was even more effective against LL/2 cells, which express both antigens." (PMID 26085010, 2015). "Based on the cell line titration test, the threshold sensitivity of Sanger sequencing is at least 10% of mutant TERT promoter-containing tumor DNA while castPCR could increase the detection limit to 2.5%." (PMID 25474136, 2014). "In this regard, a number of TERT silencing approaches proved beneficial in tumor regression." (PMID 23613993, 2013).
tumor (continued). "Growing evidence indicates that, besides the telomeric-DNA synthesis activity, TERT has additional functions in tumor development and is involved in many different biological processes, among which cellular proliferation, gene expression regulation, and mitochondrial functionality." (PMID 23061047, 2012). "Thus, a system is constructed possessing “double” tumor-specificity, which is determined by the TERT promoter (activated in tumor cells) and apoptin (which has a selective effect on tumor cells)." (PMID 22649681, 2011). "Copy number gain of 5p15 was among the most frequent changes and the minimal region of overlap harbour some 20 identified genes, among which the telomerase regulator TERT, which has previously been shown to be overexpressed in ESCC and has been associated with prognosis in other tumor types." (PMID 18405350, 2008). "Consequently, TERT repression is believed to be a pivotal tumor‐protective mechanism." (PMID 40213897, 2025). "Likewise, the multivariate analysis of tumor-related death showed that TERT amplification was a better predictor of survival than TPM, male sex, tumor multifocality or tumor size ≥ 5 cm, vascular invasion, DMs at diagnosis and/or follow-up, and stage at diagnosis I–II vs. III–IV." (PMID 40272676, 2025). "Therefore, TERT has been considered a universal tumor antigen for cancer vaccines 45-47." (PMID 40365296, 2025). "While no TERT promoter mutations were identified in this cohort, one tumor harbored a TERT mutation p.G433D, which is of unknown significance." (PMID 40270074, 2025). "Additionally to these chromosomal abnormalities, TERT mutations and common Copy-Number Variation (CNV) are known to influence tumour aggressiveness and could have potentially explained the hierarchical cluster in our proteomic data." (PMID 40562609, 2025). "Xenograft mice tumours indicated TL-induced TERT activation might be active in vivo." (PMID 41026782, 2025). "Hence, considering that TERT is expressed in 85% of tumor cells, it is intriguing to suggest that reducing the mitochondrial respiration activity might be a strategy implemented by telomerase-positive tumors to minimize ROS production." (PMID 41144538, 2025). "Likewise, our findings also evidence that TERT amplification is a better predictor of tumor-related death than TPM, male sex, tumor multifocality or tumor size ≥ 5 cm, vascular invasion, DMs at diagnosis and/or follow-up, and stage at diagnosis I–II vs. III–IV." (PMID 40272676, 2025). "Similarly, TERT promoter mutations detected in cfDNA were not indicative of tumor status (e.g., size or clinical stage) but were predictive of immunotherapy response and patient outcomes." (PMID 41002319, 2025). "Furthermore, the somatic mutation profile in this patient was atypical for Ta grade, as FGFR/TERT mutations, which are typically associated with Ta, were absent in this tumor." (PMID 38582099, 2024). "However, there was no clear association between the TERT mutation AF and tumor invasiveness or recurrence." (PMID 38607456, 2024). "The finding of a potentially subclonal TERT promoter variant in a pT1 tumor may not necessitate the need to diverge from existing guidelines, as the tumor is still considered low-risk and not in need of further treatment." (PMID 39363120, 2024). "We next analyzed whether TERT methylation was associated with any of the following clinical characteristics of PTC: patient age, gender, extrathyroidal extension, pathologic TNM, residual tumor, and stage." (PMID 38313800, 2024).